IL33 (interleukin 33)
Diseases named in the same sentence as IL33 in open-access papers (continued):
Sharing a sentence is not in itself a finding about the gene and the disease.
melanoma (continued). "Previous studies from our group and others indicate that IL-33 exerts anti-tumor effects in melanoma models by tailoring the tumor immune microenvironment." (PMID 40317004, 2025). "IL-33 administration in melanoma-bearing mice delays tumor growth by promoting intratumoral accumulation and activation of eosinophils." (PMID 40136652, 2025). "Some studies suggest that systemic administration of IL‐33 limits the growth of primary melanoma, while intranasal IL‐33 promotes lung metastasis of melanoma, through altering immune cell activity." (PMID 38775220, 2024). "Transmission electron microscopy of IL-33 activated eosinophils co-cultured with B16.F10 melanoma cells revealed the presence of multivesicular bodies (MVB) and release of EV in eosinophils upon contact with target tumor cells." (PMID 39061080, 2024). "In melanoma or pancreatic cancer models, tumoral or recombinant IL-33 increases CD103+ DCs, which activate CD8+ T-cell responses required for antitumor responses." (PMID 38825642, 2024). "In contrast, IL‐33 was found to induce an anti‐tumor effect in vivo in a melanoma mouse model in which group 2 innate lymphoid cells 2 and CD8+ T cells infiltrated the tumor tissue." (PMID 38775220, 2024). "In the context of the B16F10 melanoma model, a specific IL-33-blocking antibody has shown promise in restoring the effectiveness of anti-PD1 therapy, especially in subclones exhibiting resistance to ICIs." (PMID 39777330, 2024). "In melanoma, the overexpression of IL-33 has been shown to inhibit lung metastases by activating CD8+ T cells and NK cells." (PMID 40236667, 2024). "Particularly, two distinct murine models demonstrated that IL-33-stimulated ILC2s were able to negatively affect NK cell anti-melanoma activity and tumor rejection." (PMID 36765891, 2023). "We observed that the combination of IL-33 and anti-PD-1 antibody significantly drives anti-tumor responses toward melanoma by promoting ILC2s and cytotoxic eosinophil infiltration into tumors." (PMID 37514187, 2023). "On the other hand, a pro-tumoral role for IL-33-activated ILC2s in the context of melanoma has also been described." (PMID 36765891, 2023). "The IL-33/ILC2 axis has shown to drive anti-tumor responses in melanoma and orthotopic pancreatic tumors, and we have described the effect of IL-33 in combination with PD-1 blockade to significantly increase the anti-melanoma response." (PMID 37514187, 2023). "In melanoma and pancreatic ductal adenocarcinomas, however, IL-33-induced TILC2s play anti-tumor roles and their anti-tumorigenic functions are further enhanced by the blockade of PD-1." (PMID 37514187, 2023). "To study how IL-33 shapes immune responses in the tumor, we used a transplant mouse model of an engineered B16 melanoma cell line that overexpressed the secreted form of IL-33 (B16–IL-33)." (PMID 37611111, 2023). "In other cancer types such as pancreatic cancer, melanoma, lymphoma or colon cancer, IL-33-activated ILC2 cells were reported to bear protective functions." (PMID 37781372, 2023). "A melanoma mouse model revealed the formation of stable aggregations of eosinophils and cancer cells via IL-33 stimulation." (PMID 35565423, 2022). "Although most studies have reported IL‐33 as a tumor promoter, conflicting studies have described the antitumor effects of IL‐33 in colon cancer, melanoma, and hepatocellular carcinoma." (PMID 35791509, 2022). "In mice intravenously injected with both B16.F10 melanoma cell lines and IL-33, ILC2s promoted infiltration of eosinophils and increased the number of lung metastasis." (PMID 35565201, 2022). "Our data demonstrate that tissue specialization of IL-25-responsive tumor-promoting intestinal ILC2s have opposite functions to the tissue-specific IL-33-activated ILC2s that are protective in orthotopic pancreatic cancer and melanoma." (PMID 35658010, 2022). "In mice, the anti-tumor effects of IL-33/ILC2/eosinophil axis can be impaired by lactic acid produced by melanoma." (PMID 35720302, 2022).
melanoma (continued). "Treatment with IL-33 alone or the combination of IL-33 with PD-1 blockade boosted the cytotoxicity of hILC2s and anti-tumor activity in a mouse model of melanoma." (PMID 36246629, 2022). "Just recently, activation of eosinophils via IL-33 stimulation was shown to result in stable aggregation with cancer cells in a melanoma mouse model." (PMID 35565423, 2022). "Using the matched‐pairs of primary human melanoma cells and TILs as examples, we demonstrate that the IL‐33‐primed macrophages acquire immunosuppressive ability to inactive TIL‐mediated killing." (PMID 34486239, 2021). "Transgenic expression of IL-33 in metastasis models for B16 melanoma and Lewis lung carcinoma resulted in increased recruitment of cytotoxic NK cells to the lung site that limited metastatic progression." (PMID 34209038, 2021). "In the primary melanoma sub-cohort, the expression level of IL-33 in samples from younger patients is higher than that in samples from elder patients." (PMID 33621202, 2021). "In mice bearing melanoma, administration of interleukin 33 (IL-33) delays tumor growth and prevents pulmonary metastasis through recruiting and activating eosinophils." (PMID 34359674, 2021). "Excluding IL-33, we found that 1158, 1366, and 1012 genes are expressed at higher levels in the high IL-33 group than in the low IL-33 group in the primary melanoma, LN metastasis, and other metastasis sub-cohorts, respectively." (PMID 33621202, 2021). "The role of IL-33 in melanoma has been investigated in mouse models extensively, but only to draw controversial conclusions." (PMID 33621202, 2021). "IL-33 treatment and its tumoral expression in a mouse model for melanoma restricted tumor growth, which was abrogated by the depletion of eosinophils using monoclonal antibodies." (PMID 34209038, 2021). "Taken together, these in vivo experiments demonstrate that MMP‐9 is the key mediator of immunosuppression by IL‐33‐macrophages and it targets both STILs and melanoma cells." (PMID 34486239, 2021). "Here, it is shown that interleukin‐33 (IL‐33)‐activated macrophages protect melanoma cells from tumor‐infiltrating lymphocyte‐mediated killing." (PMID 34486239, 2021). "In the primary melanoma sub-cohort, the IL-33 expression level is positively correlated with the abundance of epithelial cells, keratinocyte, and smooth muscle cells." (PMID 33621202, 2021). "The expression level of IL-33 in primary melanoma samples is less correlated to the immune cell components in TME and has no prognostic value in patients." (PMID 33621202, 2021). "Together, these findings provide compelling evidence that MMP‐9 released by IL‐33‐stimulated macrophages mediates the immunosuppressive effects and protects melanoma cells from the STIL‐executed killing." (PMID 34486239, 2021). "In a pulmonary metastasis model derived from murine melanoma, IL-33 enhanced the frequency of CD8+ T cells expressing CTLA-4, PD-1, and KLRG-1." (PMID 34209038, 2021). "IL-33 was identified as a key factor provided locally by reprogrammed iCAFs that fuels the activity of antitumor T cells and thereby facilitates curative melanoma treatment." (PMID 34354077, 2021). "These in vivo findings provide convincing evidence that the immunosuppressive effects of the IL‐33‐aumented macrophages are executed in both melanoma cells and TILs." (PMID 34486239, 2021). "The differences of pathways enriched in the high IL-33 group between the primary melanoma and the metastasis sub-cohorts also reveal the context-specificity of IL-33’s effects." (PMID 33621202, 2021). "Although the role of IL-33 in cancer immunity remains controversial, it appears that this alarmin has beneficial effects in certain types of experimental tumors, particularly melanoma." (PMID 33329534, 2020). "Injection or tumor expression of IL-33 in melanoma-bearing mice inhibited tumor growth and this effect was abolished upon eosinophil depletion by injections of anti-Siglec-F mAb." (PMID 33329534, 2020).
melanoma (continued). "IL-33 restricts tumor growth and inhibits pulmonary metastasis in melanoma-bearing mice through eosinophils." (PMID 32410845, 2020). "Lastly, IL-33 also promotes the differentiation of IL-9-producing Th cells, which exert potent antitumor activity in certain solid cancers, such as melanoma." (PMID 33329534, 2020). "When IL-33-activated basophils were co-cultured with metastatic B16-F10 melanoma cells, tumor cell-growth was substantially inhibited, as compared to melanoma cells co-cultured with resting basophils." (PMID 33013885, 2020). "Our observations confirm data from a different study describing decreased growth of melanoma only when tumor cells were co-injected with IL-33-activated eosinophils." (PMID 32923137, 2020). "We further investigated the effects of IL-33 on granule convergence and degranulation of eosinophils in vivo in a mouse melanoma model." (PMID 31717819, 2019). "Our previous studies indicated that injection of IL-33 in mice bearing B16.F10 melanoma tumors determined massive infiltration of eosinophils in vivo." (PMID 31717819, 2019). "We previously reported that IL-33 exerts anti-tumoral activities against melanoma growth and metastasis by facilitating the recruitment of eosinophils, which were crucial for therapeutic efficacy." (PMID 31717819, 2019). "In support of this view, we demonstrate that co-injection of IL-33 EO with melanoma cells delays tumor outgrowth in mice." (PMID 31717819, 2019). "Treatment of mice implanted with B16 melanoma tumors with IL-33 results in tumor growth delay and accumulation of intratumoral eosinophils." (PMID 31717819, 2019). "We recently showed that eosinophils play an essential role in anti-tumor responses mediated by immunotherapy with the ‘alarmin’ intereukin-33 (IL-33) in melanoma mouse models." (PMID 31717819, 2019). "Injection of IL-33 into mice-bearing subcutaneous B16-F10 melanoma cells resulted not only in significant attenuation of primary tumor growth but also in a reduction in pulmonary metastasis." (PMID 31231372, 2019). "Here, addition of IL-33 to the lower compartment induced the migration of EO from the upper chamber only in presence of melanoma cells in the bottom chamber." (PMID 31717819, 2019). "As denoted by red fluorescence distribution, EO exhibited notable displacement towards the chambers containing IL-33-treated melanoma cells after 24 h, occupying the right-side microchannels and tumor-Matrigel chambers." (PMID 31717819, 2019). "In this device for competitive assay, PKH67 green-labeled B16 melanoma cells are loaded in the two opposite gel chambers alone or with added IL-33 and confronted for their capacity to attract PKH26 red-labeled EO, loaded into the middle fluidic chamber." (PMID 31717819, 2019). "Tumor over-expression or exogenous administration of IL-33 promotes anti-tumor immune responses in vivo in models of melanoma, acute myeloid leukemia, lung and colorectal cancer." (PMID 31717819, 2019). "In a study of mouse B16 melanoma and Lewis lung carcinoma models, IL-33 was shown to inhibit metastasis." (PMID 29499051, 2018). "Injection of IL-33 into established murine melanoma or acute myeloid leukemia models inhibits tumor growth in a CD8+ T cell-dependent manner prolonging the survival of mice." (PMID 30416507, 2018). "In mouse experimental metastasis models of B16 melanoma and Lewis lung carcinoma, transgenic expression of IL-33 in the host promoted the recruitment of cytotoxic NK cells to the pulmonary site that inhibited metastasis formation." (PMID 30483263, 2018). "This was also shown with the reduction of tumor metastasis in B16 melanoma and Lewis lung carcinoma metastatic models thanks to the transgenic expression of IL-33." (PMID 30416507, 2018). "In B16 melanoma mouse models, IL-33 administration was shown to decrease MDSCs accumulation in the spleen and tumor microenvironment." (PMID 30483263, 2018).
melanoma (continued). "DC maturation is promoted by IL-33 which increases their cross presentation ability particularly during the anti-leukemia or anti-melanoma immune response." (PMID 30416507, 2018). "One study shows that IL-33 promoted the proliferation and increased the cytotoxicity of NK cells against B16 melanoma cells." (PMID 30112116, 2018). "In a melanoma mouse model, IL-33 was shown to inhibit Treg infiltration in the tumor microenvironment indirectly, through stimulation of MDSCs, which had reduced capacity to induce the differentiation or expansion of Treg cells in vitro." (PMID 30483263, 2018). "We reported that in transplantable B16 melanoma models, IL-33 restricted tumor growth and inhibited lung metastasis through recruitment and activation of eosinophils." (PMID 30483263, 2018). "In mouse melanoma models, eosinophil recruitment induced by Tregs depletion or by IL-33 treatment mediated melanoma regression through production of CD8+ T cell attracting chemokines (i.e., CXCL9, CCL10 and CCL5) by promoting tumor-reactive CD8+ T cell responses." (PMID 40050933, 2025). "Although the impact of IL-33 in immune cell function in melanoma remains unclear, it has been shown to foster a tumor microenvironment that promotes melanoma growth." (PMID 40647405, 2025). "Since tumor cells can be a source of IL-33, we analyzed whether DAC could directly induce IL-33 expression in melanoma cells." (PMID 40317004, 2025). "Overall, our studies underscore an important role for IL-33/ST2 in driving tumor-immune cross talk and indicate DAC as a positive regulator of this axis that can further increase anti-tumor effects of IL-33 in combinatorial approaches against melanoma, including the use of ICB." (PMID 40317004, 2025). "Our findings indicate that DAC effectively co-operates with IL-33/ST2 axis against melanoma through immune cell recruitment and epigenetic regulation of gene expression, thus remodeling the tumor immune microenvironment to overcome resistance to PD- 1 inhibition." (PMID 40317004, 2025). "Moreover, the accumulation of eosinophils in melanoma from DAC/IL-33 treated mice was significantly superior with respect to single treatments and untreated controls." (PMID 40317004, 2025). "Additionally, the induced expression of IL-33 in tumors can enhance anti-melanoma immune responses via IFN-γ-producing CD8+ T cells and NK cells, presenting potential opportunities for cancer therapy." (PMID 40236667, 2024). "Other studies in mouse models demonstrated that overexpression of IL‐33 could inhibit melanoma lung metastasis by activating CD8+ T cells and NK cells." (PMID 38775220, 2024). "Hence, IL-33-activated basophils co-cultured with B16.F10 melanoma cells were shown to inhibit tumor growth compared to melanoma cells co-cultured with un-stimulated basophils." (PMID 37205111, 2023). "These conflicting effects of ILC2s on melanoma observed in vivo may be due to the different protocols used to stimulate ILC2s with IL-33, largely varying in terms of the amount, way and scheduling of administration." (PMID 36765891, 2023). "In a melanoma model transfected to express IL-33, CD90+ST2+ ILC2s expressed CD73." (PMID 35565201, 2022). "Moreover, IL-33-activated basophils co-cultured with B16.F10 melanoma cells, inhibited tumor cell-growth compared to melanoma cells co-cultured with unstimulated basophils." (PMID 36578500, 2022). "In a melanoma mouse model, IL-33-activated TILC2s recruit eosinophils by producing GM-CSF." (PMID 35720302, 2022). "Studies of mouse models of melanoma have recently found that eosinophils recruited by ILC2 are associated with improved outcomes, and that boosting ILC function and eosinophil recruitment using combined anti-PD-1 and IL-33 induce anti-melanoma immunity." (PMID 36003398, 2022). "Interestingly, the combination of IL-33 and the PD-1 antibody showed synergistic antitumor effects on melanoma and pancreatic cancer." (PMID 35805039, 2022).
melanoma (continued). "Importantly, we have observed a significant correlation between an overall survival and the expression of IL-33 as well as an eosinophil marker SIGLEC8 in patients suffering from melanoma." (PMID 34691082, 2021). "Ectopic expression of IL-33 in melanoma cells can induce effective anti-tumor immune responses." (PMID 33621202, 2021). "Interestingly, pretreatment of STILs with the conditioned medium from the IL‐33‐stimulated MMCs completely ablated the melanoma killing effects of STILs." (PMID 34486239, 2021). "Using the RNA-sequencing (RNA-seq) data of the cutaneous melanoma samples, we aim to dissect the tumor microenvironment (TME) and explore its relationship with IL-33 in these samples, hoping to find some new clues about IL-33’s effects on melanoma and hence to provide some therapeutic implications." (PMID 33621202, 2021). "Another study found that induced tumoral expression of IL-33 could promote anti-melanoma immune responses through interferon-γ (IFN-γ) producing CD8+ T cells and NK cells." (PMID 33621202, 2021). "B16F10 melanoma tumors with diminished lactic acid production have been found greatly growth delayed and highly infiltrated by ILC2s accompanied by eosinophils following treatment with IL-33." (PMID 34691082, 2021). "Controversial roles of interleukin-33 (IL-33) have been reported in melanoma from animal studies." (PMID 33621202, 2021). "In the primary melanoma sub-cohort, comparisons of immune cell components between the high and low IL-33 tumor samples reveal minor differences, indicating that IL-33 may not exert an immune modulation role in this setting." (PMID 33621202, 2021). "In addition, IL-33-activated eosinophils gained cytotoxic functions against melanoma cells in vitro." (PMID 34209038, 2021). "The anti-melanoma effects of exogenous IL-33 could also be mediated by eosinophils and dendritic cells (DCs)." (PMID 33621202, 2021). "Another study using a B16.OVA melanoma model revealed that systemically delivered IL-33 in combination with dectin-1-activated BM-derived DCs promoted PD-1 expression in OVA-specific CD4+ T cells, suggesting modulation of PD-1 levels in T cells via DC stimulation." (PMID 34209038, 2021). "The exact role of eosinophils in melanoma remains to be determined, however, increased tumor growth and metastatic potential have been demonstrated following an antibody-mediated depletion of eosinophils in IL-33-treated mice bearing melanoma tumors." (PMID 34691082, 2021). "In the primary melanoma sub-cohort, the expression level of IL-33 is positively correlated with the abundance of epithelial cells, keratinocytes, and smooth muscle cells in the samples, indicating that IL-33 may mainly derive from these cells." (PMID 33621202, 2021). "In the metastasis sub-cohorts, the high expression of IL-33 is associated with more infiltrations of CD8+ T cells, NK cells and DCs in tumor samples, and these immune components have been proven to be important mediators of the anti-tumor effects of IL-33 in mouse melanoma models." (PMID 33621202, 2021). "As the results from this analysis are from IL-33-activated ILC2s, we questioned whether NFκB upregulation was present in the ILC2s of our B16 melanoma model." (PMID 34531874, 2021). "The role of IL-33 in melanoma still needs to be further explored." (PMID 33621202, 2021). "Several groups have previously reported IL-33 to be present in the melanoma tumor microenvironment, though it is unclear whether the IL-33 is secreted from the melanoma cells themselves or the lung epithelial layer due to injury." (PMID 34531874, 2021). "In addition, IL-33 can facilitate the differentiation of IL-9 producing Th cells (Th9), conferring their anti-tumor response in melanoma." (PMID 34209038, 2021). "Similarly, in our melanoma models, exogenously administered IL-33 activated mDCs in the TME, promoting cross-presentation of tumor antigen in a ST2/MyD88/STAT1-dependent fashion and restoring a competent anti-tumor T cell activity." (PMID 34209038, 2021).